INS (insulin)
Diseases named in the same sentence as INS in open-access papers (continued):
Sharing a sentence is not in itself a finding about the gene and the disease.
Insulin resistance (continued). "Insulin resistance is increased during obesity and initially compensated for by pancreatic β-cells through hypersecretion of insulin." (PMID 32079203, 2020). "Fasting blood glucose and insulin levels were detected to analyze the HOMA-IR of rats to monitor the insulin resistance of T2DM rats." (PMID 31938037, 2020). "Insulin resistance index, considering basal glucose and insulin in serum, showed a progressive increase in prediabetic (11.5 ± 4.6) and BAR-1-treated mice (10.4 ± 4.6) compared with control mice (8.1 ± 2.1)." (PMID 32132523, 2020). "The higher amount of insulin resistance observed in overweight or obese mothers at early gestation was accompanied by increased basal and total insulin secretion during the OGTT." (PMID 33374430, 2020). "Corilagin acts by enhancing peripheral glucose utilization and stimulating pancreatic β cells to produce insulin while myricetin enhances intracellular protein activity, encouraging glucose uptake consequently reduces insulin resistance." (PMID 33293987, 2020). "Chronically elevated levels of insulin (hyperinsulinemia) are believed to have a primary role in exacerbating and even initiating insulin resistance and the further development of frank T2D." (PMID 32718202, 2020). "HOMA-IR was increased in postpartum normal glucose tolerance (NGT), prediabetes, and T2DM (1.64 vs. 2.14 vs. 4.27, β were used to assess insulin resistance and insulin secretion levels with different glucose statuses." (PMID 32184821, 2020). "Hyperinsulinemia has been suggested to be a compensatory mechanism for an insufficient metabolic response to insulin, leading to insulin resistance (IR)." (PMID 33644105, 2020). "Glucose tolerance and insulin resistance tests revealed decreased glucose tolerance (P < 0.01) and increased insulin resistance (P < 0.01) in the HF group pups, respectively." (PMID 32116778, 2020). "Originally, insulin resistance occurs in the skeleton muscle; however, later on, these mice become insulin resistant not only in the adipose tissue but also the liver." (PMID 32878147, 2020). "Insulin resistance means that cells cannot react appropriately to normal insulin levels, leading to hyperinsulinemia." (PMID 33266423, 2020). "In our study, the diabesity model was successfully established that exhibited a significant increase in fasting blood glucose levels compared to normal rats which signifies insulin resistance/insufficient insulin release." (PMID 33178838, 2020). "In obese mice, during insulin resistance, glucagon is increased and results in the release of higher levels of calcium, which induces calcium signaling leading to induction of higher insulin signaling." (PMID 32899471, 2020). "We can confirm the relief of insulin resistance as well as glucotoxicity from the profile of insulin shot and glucose levels during N-SIIT." (PMID 32005949, 2020). "MEG3 aggravated palmitate-induced insulin resistance by regulating miR-185-5p/Egr2 axis as a ceRNA in insulin-resistant hepatocytes." (PMID 33224264, 2020). "Previous research has relied on measurements of systemic IR based on blood glucose and insulin values, such as the Homeostatic Model of Insulin Resistance (HOMA-IR) assessment." (PMID 33519369, 2020). "Hepatic gluconeogenesis, which is normally inhibited by insulin, is increased in insulin resistance in cats." (PMID 32500084, 2020). "Total- but not HMW adiponectin concentration was negatively correlated with blood pressure, fasting insulin, fasting blood sugar and Homeostatic Model Assessment for Insulin Resistance." (PMID 31552725, 2020). "Consistent with this paradigm, estrogen treatment reverses pathway-selective insulin resistance in ovariectomized animals by promoting the activity of insulin on glucose metabolism and limiting hepatic steatogenesis." (PMID 32354182, 2020). "In obesity and insulin resistance, the skeletal muscle capillary network is compromised, impairing insulin‐mediated capillary recruitment." (PMID 33038072, 2020).
Insulin resistance (continued). "The CB is overactivated in prediabetic patients, and the variables related to CB chemosensitivity significantly correlate with fasting plasma insulin levels and Homeostatic Model Assessment for Insulin Resistance (HOMA-IR)." (PMID 32698380, 2020). "It has been shown that improvement of hepatic insulin resistance is an important factor in combination with adequate postprandial insulin response explaining the metabolic effect of RYGB34,35." (PMID 32934313, 2020). "This new finding not only establishes the key role of adipose tissue in regulating insulin resistance but also provides a useful method to impute insulin resistance estimates to human transcriptome cohorts." (PMID 32925908, 2020). "T2DM is a complex metabolic disorder, with the initial hallmarks of insulin resistance and progressive impairment in insulin secretion from the pancreas." (PMID 32758236, 2020). "Although fasting glucose levels were within a normal range for both groups on HCD, the HCD led to the increase of fasting insulin levels suggesting the development of hyperinsulinemia and insulin resistance in rats of both genotypes." (PMID 31964387, 2020). "In mouse models of obesity, abatacept was shown to improve insulin resistance, and small case report and observational studies have suggested an insulin sensitizing effect of abatacept in patients with RA." (PMID 32914050, 2020). "Defects in insulin signaling and disordered glucose and lipid metabolism account for the progression of insulin resistance." (PMID 32188147, 2020). "With progressive de-sensitization (insulin-resistance), the pancreas is required to produce increasingly higher levels of insulin (hyperinsulinemia) to achieve glucose homeostasis and prevent hyperglycemia." (PMID 32153503, 2020). "In this study, EA treatment inhibited DHEA-induced insulin resistance as confirmed by decreasing serum insulin level and HOMA-IR index, and this effect was reversed by 3-MA." (PMID 32698821, 2020). "The garlic consumption in MetS also leads to a decrease in glucose levels with reduced insulin resistance and increased insulin sensitivity, which was obtained as well in our study after the introduction of DATS." (PMID 33265949, 2020). "Free androgen index, GLU-INS ratio, and homeostasis model assessment-insulin resistance (HOMA-IR) were calculated." (PMID 31654312, 2020). "Based on the fasting levels of blood glucose and serum insulin, we also evaluated the effect of treatment on insulin resistance with the help of HOMA-IR." (PMID 31929574, 2020). "In an animal experiment, it is considered that the mass consumption of HFD contribute to insulin resistance where cells fail to respond normally to the hormone insulin." (PMID 32238886, 2020). "Insulin resistance represents a state of relative unresponsiveness of peripheral tissues to react accordingly to increasing amounts of insulin in the circulation, resulting in chronically elevated blood glucose levels." (PMID 32591906, 2020). "The homeostasis model assessment 2 model was used to determine the insulin resistance index, and fasting adiponectin, leptin, insulin, c-peptide, glucose, HbA1c, and lipid profiles were analysed." (PMID 32092909, 2020). "In T2DM, IAPP is overproduced together with insulin in pancreatic islet β cells in order to compensate for insulin resistance, which promotes formation of islet amyloid deposits." (PMID 32604774, 2020). "Another factor influencing insulin resistance during puberty is an increased secretion of growth hormone (GH), which opposes insulin." (PMID 32378377, 2020). "There was also significantly greater improvement in HOMA-IR following the VLCD which is thought to primarily reflect hepatic insulin resistance since this value is derived from fasting glucose and insulin." (PMID 32817749, 2020). "Our study showed that a history of ACEs is related to higher insulin levels and greater insulin resistance in patients with schizophrenia spectrum disorders." (PMID 33255883, 2020).
Insulin resistance (continued). "Treatment of AML-12 cells with curcumin (50 μM) for 2 h attenuated the iron overload-induced insulin resistance and improved insulin signaling." (PMID 31906278, 2020). "Insulin resistance occurs when a greater than normal amount of insulin is required to elicit a quantitatively normal response." (PMID 33210059, 2020). "Skeletal muscle plays an important role in the pathogenesis of insulin resistance as it is responsible for the major part (>80%) of insulin-stimulated whole body glucose disposal." (PMID 32987623, 2020). "The main adaptive mechanism activated with insulin resistance involves insulin secretion, which is upregulated, i.e., for the same glucose concentration the β cells secrete more insulin." (PMID 33324238, 2020). "Circadian misalignment, a typical feature of jet lag and shift work, induces insulin resistance in humans, and elevates serum glucose and insulin levels in rats." (PMID 32334629, 2020). "We found that aging triggered signs of insulin resistance characteristics in rats at 72 age weeks includingmarked insulin reduction, hyperglycemia and increased HOMA-IR." (PMID 32779434, 2020). "Insulin resistance describes the inability of cells to activate the insulin signalling pathway effectively; leading to pathological effects in multiple organ systems including the kidney." (PMID 33458251, 2020). "In this study, we elucidated how miR-27 expression affects insulin signaling in the liver and its contribution to the development of hepatic insulin resistance in high lipid concentration environments." (PMID 33212990, 2020). "This leads to insulin resistance, a condition characterized by impaired response to insulin that results in elevated levels of blood glucose." (PMID 31910742, 2020). "Insulin resistance is an important risk factor for NAFLD, and the metabolism of carbohydrates and lipids is regulated by blood glucose levels and insulin." (PMID 33114589, 2020). "Blood insulin levels and insulin resistance reinforce each other in a vicious circle that eventually leads to hyperglycaemia." (PMID 32085772, 2020). "In T2DM, the associated hyperglycaemia can be due to inadequate pancreatic insulin production or a weak cellular response to insulin signalling (i.e., insulin resistance)." (PMID 32653024, 2020). "The same study also suggested that while SM C18:0 positively correlated with insulin resistance, other SM species (C14:0, C22:3, and C24:4) are positively related to insulin secretion." (PMID 32586392, 2020). "Insulin resistance, a key component of T2D pathophysiology is defined as a state with decreased metabolic actions of insulin in target tissues, namely liver, skeletal muscle, and adipose tissue." (PMID 33198288, 2020). "Insulin resistance or impairment of insulin sensitivity has both a genetic and an environmental background." (PMID 33153226, 2020). "Generally, PKCs and PKD3 block insulin signaling at different levels contributing to the development of insulin resistance and regulate hepatic lipogenesis contributing to the development of liver steatosis." (PMID 32466765, 2020). "The genes from this cluster are involved in pathways relating to insulin resistance, insulin signaling, AMPK (adenosine monophosphate-activated protein kinase) signaling, and FOXO signaling." (PMID 33255249, 2020). "With this rationale, researchers calculated the adipose insulin resistance index (i.e., adipose-IR) by multiplying fasting plasma insulin levels with fasting plasma free fatty acids levels." (PMID 32961669, 2020). "Microbial pathogens such as Salmonella typhimurium lower insulin clearance and promote insulin resistance in mice." (PMID 32860984, 2020). "Global or hepatic insufficiency of miR-29 potently prevents the onset of diet-induced insulin resistance by negatively regulating insulin signaling via PIK3R1 regulation, suggesting that miR-29 is an important regulatory factor in metabolism homeostasis." (PMID 33195407, 2020).
Insulin resistance (continued). "Most studies on phytoestrogen intake and cardiometabolic hormones have evaluated insulin and insulin resistance (HOMA-IR) in postmenopausal women." (PMID 32824177, 2020). "Avoiding an LPO increase is a basic way to avoid the consequences of insulin resistance because excessive ROS production potentiates the insulin signal impairment induced by obesity." (PMID 32151028, 2020). "Insulin resistance observed in TSOD mice is likely due to disturbance of insulin-initiated translocation of glucose transporter type 4, non-insulin-dependent diabetes (Nidd) 4, Nidd5, and Nidd6." (PMID 33092030, 2020). "On the contrary, EC‐specific inhibition of Notch signaling increased insulin sensitivity and improved glucose tolerance and glucose uptake in muscle in a high‐fat diet‐induced insulin resistance model." (PMID 32187826, 2020). "T2DM is a metabolic disease characterized by chronic hyperglycaemia that is related to both insulin resistance and defective insulin secretion." (PMID 32714070, 2020). "Studies suggest that lipid accumulation in skeletal muscle impairs tissue-specific insulin sensitivity and ultimately leads to insulin resistance in the whole organism." (PMID 33115498, 2020). "Excess lipid metabolites trigger a number of different serine kinases with subsequent impairments of insulin signaling or prevent activation of Akt2, resulting in insulin resistance." (PMID 32158492, 2020). "Insulin resistance refers to a pathological condition that results in abnormally low insulin sensitivity at the physiological insulin levels, which eventually leads to hyperinsulinemia." (PMID 32549999, 2020). "Theoretically, children with prediabetes HbA1c potentially have higher insulin secretion to compensate with insulin resistance." (PMID 33224197, 2020). "In a systemic insulin resistance state, the insulin signalling within glucose recipient tissues is therefore defective, and in this case, hyperglycaemia perseveres." (PMID 32927739, 2020). "The ingestion of a HFD for 18 weeks induced a significant increase in glucose and insulin serum levels as well as in the insulin resistance index, the HOMA index, compared to the control animals (p < 0.05)." (PMID 32523094, 2020). "HepG2 cells were induced to IR (insulin resistance) with insulin (10−6 M) treatment for 24 h, and effect of A22 on cellular glucose intake was measured by using confocal imaging." (PMID 32710621, 2020). "Plasma citrulline was significantly reduced in men with insulin resistance and T2D compared to insulin sensitive men." (PMID 32292494, 2020). "It was also observed that compared with the cases with CAC = zero, those with CAC > zero had age, WC modestly higher, although not differing as to BMI, BP, glucose, hemoglobin A1c (HbA1c), insulin, and homeostasis model assessment-insulin resistance (HOMA-IR)." (PMID 32579186, 2020). "After a 6-month intervention in 60 healthy women, a decrease in insulin and insulin resistance was observed." (PMID 32824177, 2020). "We assessed insulin sensitivity by hyperinsulinaemic euglycaemic clamp to confirm the severity of insulin resistance." (PMID 32755965, 2020). "Insulin resistance refers to various reasons that reduce the efficiency of insulin in promoting glucose uptake and utilization." (PMID 33083291, 2020). "Overexpression (2–3 fold) of PDE3B and special diet (HFD) in RIP-PDE3B/2 mouse contributed to hyperglycemia, pancreatic dysfunction of islets, intolerance of glucose, and insulin resistance, which developed suddenly and blunted insulin secretion." (PMID 33153226, 2020). "Whereas gene expression of Slc2a8 is reduced in mouse models of autoimmune type 1 diabetes, GLUT8 expression increases in insulin resistance and type 2 diabetes, suggesting that the expression is regulated by insulin." (PMID 32591906, 2020).
Insulin resistance (continued). "Obesity in chow-fed p62Δ69-251 mice is primarily the result of increased body fat with only a slight (but significant) increase in lean tissue mass, and is accompanied by glucose intolerance, elevated fasting levels of insulin and insulin resistance." (PMID 32385399, 2020). "An increase in free fatty acids is associated with defective fatty acid oxidation, which induces or aggravates insulin resistance in adipose, liver, and muscle tissue by directly or indirectly generating metabolites and altering insulin signaling." (PMID 33009367, 2020). "Insulin resistance is the state in which responses of peripheral target tissues, including skeletal muscle, adipose tissue, and liver, to the physiological level of insulin are reduced." (PMID 33339212, 2020). "improve glucose metabolism and insulin resistance, improve the function of the islet beta cells secrete insulin." (PMID 32957320, 2020). "Chronic hyperglycemia is a manifestation of insulin resistance which is a pathological condition characterized by insulin's decreasing efficacy at lowering blood glucose levels." (PMID 31998807, 2020). "The role of hyperinsulinemia and prolonged exposure to high insulin in β-cell insulin resistance and decompensation is still unclear and widely debated." (PMID 32150819, 2020). "Both insulin and glucose levels were measured to determine the level of insulin resistance in this cohort." (PMID 32858953, 2020). "HOMA-IR is an index that corresponds to fasting glucose and insulin concentrations and highly relates to hepatic insulin resistance." (PMID 32566685, 2020). "As insulin resistance progresses to type II diabetes, enhanced levels in blood insulin and Hb1Ac have been detected after chronic intake of an HFD." (PMID 32947952, 2020). "Whereas hypertrophy promotes adipose tissue inflammation and insulin resistance, hyperplasia results in smaller adipocytes and goes along with less adipose tissue inflammation and better insulin sensitivity." (PMID 32385276, 2020). "An accumulating body of evidence suggests that intramyocellular accumulation of lipid metabolites directly leads to insulin resistance, via defects in insulin signaling and reduced insulin-stimulated glucose-transport activity." (PMID 32161551, 2020). "Insulin resistance means the physiological doses of insulin cannot get their normal biological effects, and decrease the uptake and utilization of glucose." (PMID 32425786, 2020). "The metabolic benefits in patients with established type 2 diabetes were quite convincing, with marked improvements in fasting insulin, glucose, and HbA1c levels as well as a reduction in insulin resistance according to HOMA-IR." (PMID 32314253, 2020). "Insulin resistance is a common pathological condition in obesity and type 2 diabetes, which is characterized by an impaired response to insulin in peripheral tissues." (PMID 32438641, 2020). "One reason for this inconsistency is that overweight and obese children are usually highly insulin resistant and thus more likely to show the beneficial effect of lifestyle interventions on insulin resistance than normal-weight children." (PMID 32816094, 2020). "Fasting plasma insulin (10.6 ± 7.1 vs. 13.7 ± 17.8 μIU/mL, p = 0.021) and homeostatic model assessment of insulin resistance (HOMA-IR) index (2.6 ± 1.8 vs. 3.4 ± 5.6, p = 0.039) were significantly lower in the low BDNF group than in the high BDNF group." (PMID 32679912, 2020). "This was further supported by the study by Arunkumar and Anuradha, who mentioned that genistein improved insulin action in the muscle by targeting AMPK in a high fructose diet fed-mice model of insulin resistance." (PMID 33255206, 2020). "Instead, specific loss of VAT Tregs leads to improved fasting glucose and insulin levels in aged (36‐week‐old) mice, suggesting an opposing role for VAT Tregs in age‐associated insulin resistance." (PMID 32463116, 2020).